ADCY1 (adenylate cyclase 1)
Diseases named in the same sentence as ADCY1 in open-access papers (continued):
Sharing a sentence is not in itself a finding about the gene and the disease.
autism (2 papers, 2017 to 2022). Persistent deficits in social interaction and communication and interaction as well as a markedly restricted repertoire of activity and interest as well as repetitive patterns of behavior. "Together, these results demonstrate that genetic deletion of Adcy1 in Fmr1 KO mouse rescues several well-characterized autism-related symptoms." (PMID 28218269, 2017). "Genetic reduction of Adcy1 also ameliorates autism-related symptoms including repetitive behaviour, defective social interaction and audiogenic seizures." (PMID 28218269, 2017). "Interestingly, FMR1-null mice, a rodent model of fragile X syndrome, exhibited increased ADCY1 expression and ADCY1-overexpression-like phenotype, including enhanced autism-related behaviors and increased ERK1/2 activity." (PMID 35307032, 2022). "Moreover, we demonstrate that hyperactivity of ADCY1-directed neuronal signalling is causative for autism-related core behavioural abnormalities in the Fmr1 KO mouse model of FXS, which can be reversed by genetic and pharmacological reduction of ADCY1." (PMID 28218269, 2017). "Consistent with the higher seizure susceptibility in autism and FXS patients, Fmr1 KO mice showed audiogenic seizures (AGS), which were absent in WT and Adcy1 KO mice." (PMID 28218269, 2017). "In contrast, genetic deletion of Adcy1 alone (in Adcy1 KO mice) did not alter these autism-related behaviours." (PMID 28218269, 2017). "Notably, Adcy1 KO mice display no autism-related behaviour, the therapeutic correction on behaviour by genetic and pharmacological manipulation of ADCY1 is specific when neuronal signalling is exaggerated." (PMID 28218269, 2017). "Here, we find that Adcy1 mRNA translation is aberrantly increased in the absence of FMRP and altered ADCY1 expression contributes to the enhanced ERK1/2 signalling and autism-related behaviours in Fmr1 KO mice." (PMID 28218269, 2017).
dementia (2 papers, 2016 to 2022). Loss of intellectual abilities interfering with an individual's social and occupational functions. "PGR and ADCY1 have been associated with neurodevelopment, but a direct link with dementia or neurodegeneration has not been found." (PMID 36389068, 2022).
diabetes (2 papers, 2022 to 2024). "Several switch genes, including AKT3, LAMA2, ADCY1, RAB3A, RAPGEF4, and ABCC8, have been implicated in insulin signaling and diabetes." (PMID 36389068, 2022). "To confirm this, we then analyzed several known clock-controlled genes for the retina (Adcy1, Drd4, Nr2e3, Cys1, Plekbh1, Usp2) that also showed amplitude changes but no phase changes, indicating that the retinal clock was entrained to the 12L:12D cycle at this stage of diabetes." (PMID 38039846, 2024).
esophageal cancer (2 papers, 2019). A primary or metastatic malignant neoplasm involving the esophagus. "Fortunately, ADCY1 target drugs improve prognosis for esophageal carcinoma patients, which suggests that these drugs may also help FPA patients." (PMID 31655798, 2019). "In addition, ADCY1 overexpression promotes multi drug-resistant esophageal carcinoma-1." (PMID 31655798, 2019).
fragile X syndrome (2 papers, 2022). A genetic syndrome caused by mutations in the FMR1 gene which is responsible for the expression of the fragile X mental retardation 1 protein. "Hyper-expression of ADCY1 has been identified in a mouse model of Fragile X syndrome (FXS), which is predominantly caused by mutations in the FMR1 (Fragile X messenger ribonucleoprotein 1) gene and deficient expression of its gene product FMRP (FMR1 protein)." (PMID 36188604, 2022).
metastatic melanoma (2 papers, 2022 to 2025). A melanoma that has spread from its primary site to another anatomic site. "It has been shown that metastatic melanomas express more ADCY1 mRNA than primary melanomas and that a high level of ADCY1 expression correlates with a poorer prognosis." (PMID 35158973, 2022).
myopia (2 papers, 2023 to 2025). "Therefore, through clinical samples of high myopia, we further demonstrated that miR-760-3p/Adcy1 in the retinas of adults with high myopia may be associated with the scleral remodeling-related ERK-MMP-2 pathway." (PMID 37932794, 2023). "We further explored the potential connection between miR-760-3p/Adcy1 and scleral remodeling in the sclerae of adults with high myopia." (PMID 37932794, 2023). "Given further verification in FDM guinea pigs, FDM mice, and highly myopic adults, we propose that lncRNA-XR_002792574.1 may be involved in the development of myopia through the miR-760-3p/Adcy1 pathway in RGCs." (PMID 37932794, 2023). "To explore whether the retina is hypoxic in myopia and whether the lncRNA-XR_002792574.1/miR-760-3p/Adcy1 axis in RGCs is related to retinal hypoxia, we detected the expression of HIF-1a in the retina." (PMID 37932794, 2023). "On the one hand, the lncRNA-XR_002792574.1/miR-760-3p/Adcy1 axis might inhibit the cGMP/PKG and apelin signaling pathways in RGCs, thereby causing RGC damage in myopia." (PMID 37932794, 2023). "We demonstrated that the lncRNA-XR_002792574.1/miR-760-3p/Adcy1 axis in RGCs might be related to myopia." (PMID 37932794, 2023). "Via lncRNA-mediated ceRNA network construction and PCR verification, we found that lncRNA-XR_002792574.1 may be involved in the development of myopia through the miR-760-3p/Adcy1 pathway in RGCs." (PMID 37932794, 2023). "Altogether, these results indicate that lncRNA-XR_002792574.1 may be involved in the development of myopia through the miR-760-3p/Adcy1 pathway in RGCs." (PMID 37932794, 2023). "Therefore, we demonstrated that the lncRNA-XR_002792574.1/miR-760-3p/Adcy1 axis in RGCs might be related to myopia." (PMID 37932794, 2023). "In conclusion, these findings indicate that miR-760-3p/Adcy1 may be involved in the development of myopia in highly myopic adults, that the cGMP/PKG pathway in highly myopic adults is inhibited, and that the apelin pathway shows a downward expression trend in highly myopic adults." (PMID 37932794, 2023). "Our previous study revealed that the lncRNA-XR_002792574.1/miR-760-3p/Adcy1 axis inhibited the cGMP/PKG and apelin signaling pathways in RGCs, resulting in myopia-related RGC damage." (PMID 39894836, 2025). "In future myopia studies, we plan to further verify whether inhibiting lncRNA-XR_002792574.1 regulates the cGMP/PKG and apelin signaling pathways in RGCs and scleral remodeling via miR-760-3p/Adcy1, thereby delaying myopia progression." (PMID 37932794, 2023).
non-small cell lung carcinoma (2 papers, 2024). A group of at least three distinct histological types of lung cancer, including non-small cell squamous cell carcinoma, adenocarcinoma, and large cell carcinoma. "For example, ADCY1 was responsible for catalyzing ATP to cyclic AMP (cAMP) and could influence platinum-based chemotherapy response in non-small cell lung cancer (NSCLC)." (PMID 39319137, 2024).
pulmonary fibrosis (2 papers, 2020 to 2024). Chronic progressive interstitial lung disorder characterized by the replacement of the lung tissue by connective tissue, leading to progressive dyspnea, respiratory failure, or right heart failure. "Based on above findings, we further identified key genes (ADCY1, ADCY5, ADCY8) in cAMP signal pathway and Rap1 signal pathway which were potentially regulated by the treatment of AS in BLM‐induced pulmonary fibrosis." (PMID 32548952, 2020). "To validate the effect of AS on the expression of the five key genes (ADCY1, ADCY5, ADCY8, cAMP and Rap1) in cAMP and Rap1 signal pathways in pulmonary fibrosis, we measured their expression at gene level and protein level by RT‐qPCR and ELISA experiments, respectively." (PMID 32548952, 2020).
cognitive decline (1 paper, 2025). "Thus, high-intensity interval training appears to counteract cognitive decline by reinstating a coordinated gene network with Arc and Egr1 to initiate synaptic transcriptional programs and Adcy1 to restore intracellular signaling, culminating in improved memory-related neural plasticity." (PMID 41516177, 2025).
colon cancer (1 paper, 2021). "Firstly, bioinformatic prediction results in our study indicated that DPP10-AS1 and ADCY1 were poorly expressed, while miR-127-3p was highly expressed in colon cancer." (PMID 33744851, 2021). "Compared with adjacent normal tissues, DPP10-AS1 and ADCY1 expression was downregulated, while miR-127-3p expression was upregulated in colon cancer tissues." (PMID 33744851, 2021). "Taken together, this study demonstrates that DPP10-AS1 inhibits CCSC proliferation by regulating miR-127-3p and ADCY1, providing fresh insight into a promising novel treatment strategy for colon cancer." (PMID 33744851, 2021). "Next, RT-qPCR was conducted to determine the expression of DPP10-AS1, miR-127-3p, and ADCY1 in both the colon cancer and adjacent normal tissues." (PMID 33744851, 2021). "In the current study, we set out to investigate the potential roles of DPP10-AS1 and miR-127-3p in colon cancer, with the involvement of ADCY1." (PMID 33744851, 2021). "Herein we hypothesized that DPP10-AS1 could affect the development of colon cancer via the interaction with miR-127-3p and adenylate cyclase 1 (ADCY1)." (PMID 33744851, 2021). "Moreover, based on the Pearson’s correlation coefficient, DPP10-AS1 was identified to be positively correlated with ADCY1, while both DPP10-AS1 and ADCY1 expressions were negatively correlated with miR-127-3p expression in colon cancer patients." (PMID 33744851, 2021). "The findings suggested that DPP10-AS1 could competitively bind to miR-127-3p to regulate the expression of ADCY1, thereby participating in the development of colon cancer." (PMID 33744851, 2021). "Therefore, the current study set out elucidate the regulatory role of DPP10-AS1 in colon cancer stem cells (CCSCs) via the interaction with miR-127-3p and ADCY1, with the hope to find a better effective therapy method for colon cancer." (PMID 33744851, 2021). "Meanwhile, binding sites between miR-127-3p and ADCY1 were also identified, suggesting that DPP10-AS1 involve in the progression of colon cancer by regulating ADCY1 through miR-127-3p." (PMID 33744851, 2021).
Hearing impairment (1 paper, 2019). A decreased magnitude of the sensory perception of sound. "Mutations of ADCY1 were revealed to be associated with hearing impairment or other disorders in the nervous system." (PMID 31839819, 2019).
Hepatitis C (1 paper, 2021). "Another gene in the hsa04550 pathway, GRB2, coding for Growth Factor Receptor Bound Protein 2, is associated with Hepatitis C and Hepatitis E. In turn, Calmodulin-activated adenylate cyclases (ADCY1 and ADCY8 genes) generate cAMP." (PMID 35008650, 2021).
hypertrichosis (1 paper, 2020). Excessive hair growth anywhere on the body. "Despite Adcy1 is generally linked with thermogenesis pathway, it has been recently associated to hypertrichosis in mice." (PMID 32615938, 2020).
insulinoma (1 paper, 2022). "The expression of ADCY1 and calcium channel 2 (CACNA2) greatly enhances insulinoma with a YY1T372R mutation, while they are less expressed in normal β cells." (PMID 35832555, 2022). "Accordingly, the higher expression of ADCY1 and CACNA2D2 may play a crucial role in the pathogenesis of insulinoma." (PMID 35832555, 2022).
lung adenocarcinoma (1 paper, 2024). A carcinoma that arises from the lung and is characterized by the presence of malignant glandular epithelial cells. "Through the data in the TCGA, we found that ADCY1 was overexpressed in lung squamous cell carcinoma, and it is significantly associated with the survival of lung adenocarcinoma." (PMID 39338283, 2024). "We used the gene expression data of 497 lung adenocarcinoma tissue samples and 502 lung squamous cell carcinoma tissue samples, and found that the expression level of ADCY1 in lung squamous cell carcinoma tissues was higher than that in normal tissues (p = 0.018)." (PMID 39338283, 2024).
MALT lymphoma (1 paper, 2020). An indolent, extranodal type of non-Hodgkin lymphoma composed of small B-lymphocytes (centrocyte-like cells). "Sanger sequencing of germline DNA revealed the presence of a mutant base T of PHOX2B and a mutant base C of ADCY1 in the sequence, which were discovered for the first time in MALT lymphomas involving the kidney." (PMID 33585230, 2020).
medulloblastoma (1 paper, 2016). A malignant, invasive embryonal neoplasm arising from the cerebellum. "Moreover, a recent study demonstrated that the neuropeptide pituitary adenylyl cyclase activating polypeptide (PACAP), another ADCY1 activator, inhibits proliferation of primary medulloblastoma derived tumorsphere cultures by PKA activation and inhibition of Hedgehog signal." (PMID 27188717, 2016).
Myocardial fibrosis (1 paper, 2024). "In the present study, it was also found that Adcy1 was significantly downregulated in the myocardium of the HFpEF mice, accompanied by increased myocardial fibrosis." (PMID 38710658, 2024).
neurofibroma (1 paper, 2021). An intraneural or extraneural neoplasm arising from nerve tissues and neural sheaths. "To verify the role of ADCY1 in SUZ12 mutation, we used RNA interference and plasmid transfection to interfere with SUZ12 expression in plexiform neurofibroma (pNF) and MPNST cell lines and then treated the cells with forskolin, IBMX and H89." (PMID 34692515, 2021). "In conclusion, our findings suggested that SUZ12 loss potentiates the effects of NF1 mutations by amplifying Ras signaling through the ADCY1/cAMP/Rap1/ERK pathway and that SUZ12 may serve as a therapeutic and prognostic biomarker in NF1-associated neurofibromas." (PMID 34692515, 2021).
Obesity (1 paper, 2020). Accumulation of substantial excess body fat. "We report the results of a cross-sectional study assessing circulating levels of functional ADCY1, −3 and −8 in patients with T2D vs. non-diabetic (ND) controls in association with obesity." (PMID 32847122, 2020).
osteopetrosis (1 paper, 2021). Osteopetrosis, also known as marble bone disease, is a descriptive term that refers to a group of rare, heritable disorders of the skeleton characterized by increased bone density on radiographs. "At seven loci, there was a single putative causal gene: Abca12 at a locus for adult neurogenesis; Epha4 (stress-coping strategy); Pkn2, Slit3, and Pgk1-rs7 (at three different loci for sleep); H60c (home cage activity); and Adcy1 (osteopetrosis)." (PMID 34311762, 2021).
Parkinsonism (1 paper, 2017). Characteristic neurologic anomaly resulting from degeneration of dopamine-generating cells in the substantia nigra, a region of the midbrain, characterized clinically by shaking, rigidity, slowness of movement and difficulty with walking and gait. "To clarify the traditional belief in the antiepileptic effects, and the use in neuralgia and parkinsonism of L. nobilis in folk medicine, we investigated the possible influence of the essential oil and its major components on ADCY1 expression." (PMID 28587201, 2017).
uveal melanoma (1 paper, 2025). A melanoma derived from melanocytes of the uveal tract. "We found that high-ADCY1 expression is very strongly associated with decreased survival in patients with uveal melanoma (P = 7.5 × 10−5)." (PMID 39804140, 2025).
tumor (16 papers, 2019 to 2025). "CCR4, CMA1, ADCY1, RDH12, and ENTPD2 exhibited higher expression levels in the low-risk group, indicating their possible tumor-suppressive functions." (PMID 40243888, 2025). "According to recent studies, ADCY1 in tumor drug resistance has rarely been reported, mainly related to tumor occurrence, development, and prognosis." (PMID 39338283, 2024). "DPP10-AS1 was shown to inhibit the proliferation of CRCSCs by regulating miR-127-3p and adenylate cyclase 1 (ADCY1), and to exert a tumor suppressor function in CRC." (PMID 35155247, 2022). "The low expression of ADCY1 mRNA was related to gender (P = 0.035), neoplasm histology grades (P = 0.008), and survival (P = 0.036)." (PMID 34650124, 2021). "In the independent GSE62452 dataset, the GNG7 and ADCY1 mRNA expression was incrementally downregulated with increasing tumor stages as well as neoplasm histology grades." (PMID 34650124, 2021). "Conversely, low-risk patients demonstrated higher expression of metabolic genes, such as CMA1 and ADCY1, which may enhance metabolic homeostasis and anti-tumor immunity." (PMID 40243888, 2025). "In addition, as a member of the ADCY superfamily, Adcy1 is thought to be involved in tumor angiogenesis." (PMID 37025993, 2023). "In addition, the GNG7 and ADCY1 mRNA expression was incrementally downregulated with increasing neoplasm histology grades as well as tumor stages." (PMID 34650124, 2021). "Additionally, the upregulation of ADCY1 by regulating microRNA-127-3p exerts anti-tumor effects on colon cancer." (PMID 34650124, 2021). "For these tumor types, five cancer drivers were targeted only by NPs at < 100 nM, including Adenylate Cyclase 1 (ADCY1), Matrix Metallopeptidase 2 (MMP2), Aryl Hydrocarbon Receptor (AHR), Cyclin Dependent Kinase 2 (CDK2), and Mitogen-Activated Protein Kinase 11 (MAP3K11)." (PMID 31214023, 2019). "In vitro and in vivo studies uncovered that DPP10-AS1, worked as a tumor suppressor, inhabited proliferation, migration and invasion but facilitated apoptosis of CRC cells through the potential miR-127-3p/ADCY1 axis." (PMID 35842644, 2022). "Although the genes in (PRKAA2, GNG7, MYL3, NOS1, ADCY1, PLCB1, MYLK3, and MYLK4) the apelin/APJ signaling axis are found to be downregulated and might not be considered responsible in cdRCC progression, downregulation of GNG7 tells a different story due to its tumor‐suppressive activity." (PMID 40304310, 2025).
cancer (14 papers, 2019 to 2024). A tumor composed of atypical neoplastic, often pleomorphic cells that invade other tissues. "Mutations in adenylate cyclase (ADCY1), which catalyzes ATP to cAMP, impact drug efficiencies in various cancers, such as lung cancer, esophageal cancer, and colorectal cancer." (PMID 33379194, 2020). "GNG7 and ADCY1 may be an oncogene that regulated tumorigenesis and development through pathways in cancer and could be used as a biomarker of the diagnostic and prognostic value of PAAD." (PMID 34650124, 2021). "The KEGG analysis on 13 selected genes showed that GNG7 and ADCY1 enriched in the Pathway in Cancer." (PMID 34650124, 2021). "Among the ADCY gene family members, ADCY1 is the most extensively investigated in solid cancers, where it is highly expressed in cancer tissues and related to a poor prognosis." (PMID 32568101, 2020). "We observed that two genes (GNG7, ADCY1) meaningfully enriched in the Pathways in Cancer." (PMID 34650124, 2021). "Other target genes in our study including ADCY1, BCL2, BDKRB2, CALM1, and CCND1 have been proved to play important roles in multiple pathways of cancer progression." (PMID 31775867, 2019). "The genetic algorithm uniquely identified ADCY1, currently not known to be targeted by any cancer-related drugs." (PMID 35082323, 2022). "By contrast, ADCY1 expression did not affect the prognosis of AML patients, suggesting the actions of group 2 adenylyl cyclases (ADCY2, ADCY4 and ADCY7) in AML differ from those in other cancers." (PMID 32568101, 2020). "DAG and IP3 signaling was not enriched with cancer drivers and did not have any low affinity CT drug targets, but did have six high affinity NP targets: PRKCG, E,A,D (Protein Kinase C), PDE1A (Phosphodiesterase 1A) and ADCY1 (Adenylate Cyclase 1)." (PMID 31214023, 2019).